YAP1 (Yes1 associated transcriptional regulator)
Diseases named in the same sentence as YAP1 in open-access papers (continued):
Sharing a sentence is not in itself a finding about the gene and the disease.
infection (continued). "In addition, silencing lncARSR reduced IRS expression and phosphorylation level of AKT but increased phosphorylation level of YAP1 in HepG2 cells, which was further promoted by additional infection with YAP1S127D." (PMID 32169080, 2020). "It was illustrated that IRS expression and phosphorylation level of AKT were elevated but phosphorylation level of YAP1 was diminished in HepG2 cells over-expressing lncARSR, while infection with oe-lncARSR + sh-YAP1 decreased IRS expression and phosphorylation level of AKT and YAP1." (PMID 32169080, 2020). "A report demonstrates a significant down-regulation of gga-miR-375 expression in chicken liver 20 days after infection with ALV-J, and overexpression of gga-miR-375 significantly inhibited proliferation of DF-1 cells by directly targeting yes-associated protein 1 (YAP1)." (PMID 31683847, 2019). "YAP1 transcriptionally activates IL‐1β in GC cells, which is beyond the classic mechanism involving immune cell responses, and creates a complete inflammatory environment wherein the infection occurs." (PMID 31145543, 2019). "Moreover, confocal microscopy showed that a large number of active Yap1 expression was co-localized with Krt14-positive cells, which confirmed the successful infection of lentivirus transducing active Yap1." (PMID 26695440, 2016). "Once activated, Yap1 induces U. maydis peroxidase gene expression, leading to the successful establishment of infection." (PMID 18974830, 2008). "The YAP1 and TAZ mRNA levels were significantly elevated 72 h post-infection with YAP15SA and TAZ4SA lentiviruses." (PMID 38247878, 2024). "The YAP1/TAZ targets, CTGF/CCN2, and CYR61/CCN1 also showed upregulation, suggesting successful infection of human acinar cells with YAP15SA and TAZ4SA." (PMID 38247878, 2024). "YAP1-TEAD pro-proliferation and pro-survival-related genes were found to be increased after infection." (PMID 35565411, 2022). "Compared to the control group, the infection of HCMV significantly reduced the mRNA expression of Mst1, Mst2, SAV, Lats1, Lats2, Mob1, YAP1, TAZ, TEAD1-4 genes and YAP protein expression in the Hippo-YAP pathway." (PMID 34717661, 2021). "Meanwhile, we found that knockdown of yap-1 and egl-44 reduced the expression of clec-85p::gfp after P. aeruginosa PA14 infection." (PMID 32857822, 2020). "In vivo assays, gga-miR-375 was significantly downregulated in chicken livers 20 days after infection with ALV-J, and YAP1 was significantly upregulated 20 days after ALV-J infection (P<0.05)." (PMID 24694742, 2014). "YAP1, cyclin E, and DIAP1 expression were also significantly upregulated in livers but bone marrow and spleen at 20–30 days post-infection." (PMID 24694742, 2014). "We thus examined the protein expression levels and phosphorylation status of YAP1 (pYAP1) with and without infection, along with the expression of HCMV proteins IE1/2, TEAD1, and the H3K27ac histone mark in uninfected and infected cells." (PMID 40928347, 2025). "After infection with KRAS-mCherry lentivirus, there was an upregulation of YAP1/TAZ and their targets, suggesting that KRAS may induce YAP1/TAZ expression." (PMID 38247878, 2024). "In plant fungal pathogens, several genes, such as Yap1 in Ustilago maydis and DES1 in Magnaporthe oryzae are responsible for ROS detoxification at the infection site and are required for virulence." (PMID 28232841, 2017). "Additionally, the expression of related genes differed among organs; for instance, compared to the bone marrow and spleen, which are immune organs, liver and blood had higher levels of YAP1, cyclin E, and DIAP1 expression from 20–30 days post infection." (PMID 24694742, 2014). "Studies of U. maydis also showed that Yap1 plays a critical role in the H2O2 detoxification system and in the infection of maize plants." (PMID 21383978, 2011).
infection (continued). "Additionally, the infection efficiency of YAP/HIF-1α overexpression or knockdown in the TH17 cells was evaluated and confirmed by means of RT-qPCR and Western blot analysis, where sh-YAP-1 and sh-HIF-1α-1 exhibited superior efficiency, and were thus used for further experimentation (p < 0.05)." (PMID 33980319, 2021). "However, infections by P. aeruginosa PA14 and S. Typhimurium all induced significant nuclear translocation of YAP-1/YAP in the intestine at 24 hours but not 12 hours after infection." (PMID 32857822, 2020).
adenocarcinoma (12 papers, 2015 to 2025). A common cancer characterized by the presence of malignant glandular cells. "Recent studies have identified the expression of YAP-1 in NSCLC adenocarcinomas as a potential mechanism of drug resistance." (PMID 40922739, 2025). "Human adenocarcinoma-related gene AGR2 induces bidirectional regulatory protein expression through Hippo pathway coactivator YAP1." (PMID 36147635, 2022). "The activation of AREG by AGR2 has been shown to be dependent on the Hippo pathway effector protein YAP1 in human adenocarcinoma cell lines." (PMID 31434729, 2019). "The human adenocarcinoma-associated gene, AGR2 (anterior gradient 2), induces expression of amphiregulin through activation of YAP1 in PC." (PMID 27738325, 2016). "Initially, we detected an inverse correlation of NDR2 and YAP1 protein expression in six out of ten adenocarcinoma samples." (PMID 25601544, 2015). "Furthermore, the YAP1 protein displayed a distinctive expression pattern in these EMT-associated samples, particularly within the adenocarcinoma-rich subgroup, distinguishing them from other samples." (PMID 40603978, 2025). "In comparison, only 28% of the adenocarcinoma samples demonstrated nuclear expression of MUC13 and YAP1." (PMID 37793774, 2023). "Previous work established that adenocarcinoma cell lines from the lung and esophagus are dependent on AGR2, YAP1, and AREG to maintain the transformed phenotype." (PMID 27764193, 2016).
hematologic malignancies (6 papers, 2020 to 2025). "Previous studies have shown that low levels of YAP1 can block ABL1-induced apoptosis in hematological malignancies, while the genetic inactivation of MST1 restores YAP1 levels and causes cell death, both in vitro and in vivo." (PMID 40573272, 2025). "In addition, low YAP1 levels prevent hematologic malignancies from inducing apoptosis and negatively regulate mesenchymal stem cell differentiation." (PMID 37614365, 2023). "However, it should be noted that the Hippo kinase STK4, also identified as a SYK target in DG75 cells, and YAP1, are involved in hematologic malignancies." (PMID 33670716, 2021). "Reduction of the kinase STK4 restores YAP1 and stimulates programmed cell death, giving justification for the identification of new STK4 inhibitors for clinical use in the treatment of hematologic malignancies." (PMID 33924049, 2021).
cardiac disease (5 papers, 2020 to 2025). "Thus, understanding the molecular regulation of TGFβ2-dependent ECM remodeling by YAP1 is an important step in elucidating the underlying mechanisms involved in the etiology of heart disease." (PMID 38132651, 2023). "Subsequently, studies have conclusively reported the contribution of the Hippo-YAP1/TAZ pathway in cardiac disease, specifically on the (anti-) apoptotic activity." (PMID 40131761, 2025). "Several reports have focused on the role of Hippo–YAP1/TAZ signaling in cardiac disease to explore the efficacy of leading therapeutic compounds and agents." (PMID 32390875, 2020). "The involvement of the Hippo pathway in cardiac fibrosis and remodeling explains the pernicious role of YAP1/TAZ in cardiac disease." (PMID 32390875, 2020). "The effects of long-term suppression of Hippo signaling or activation of YAP1/TAZ in cardiac disease are opposite to those of short-term suppression." (PMID 32390875, 2020). "The available evidence suggests the significance of sustaining the appropriate YAP1/TAZ protein level in therapy of cardiac disease." (PMID 32390875, 2020). "Additionally, Statins, a class of lipid-lowering medications used to prevent cardiac disease, inhibit Yap1 nuclear localization and transcriptional responses in human cancer cells." (PMID 39468013, 2024). "In addition to the proliferation of cardiomyocytes in the developmental stage, YAP1 modulates cardiac disease progression in adult heart." (PMID 36015285, 2022). "The biological effects of ubiquitinated/deubiquitinated YAP1/TAZ have been investigated mainly in tumorigenesis, and less so in cardiogenesis and cardiac disease." (PMID 32390875, 2020). "Thus, YAP1/TAZ may serve as a therapeutic target in many cardiac diseases." (PMID 32390875, 2020). "As a pathway that controls organ size, Hippo–YAP1/TAZ signaling is essential for cardiac regeneration and could be applied for cardiac regeneration and targeted therapeutics in cardiac disease." (PMID 32390875, 2020). "However, the latent regulatory network of YAP1/TAZ has not been completely elucidated in previous research, especially in the context of cardiac disease." (PMID 32390875, 2020). "However, the relationship between mechanical stimuli, remodeling/fibrosis, and YAP1/TAZ is not well characterized; therefore, studies to identify YAP1/TAZ activity and effects in cardiac disease are urgently needed." (PMID 32390875, 2020).
degenerative diseases (4 papers, 2020 to 2025). "YAP1 is a transcriptional co-activator that has been linked to neurodegenerative diseases, including AD." (PMID 37965040, 2023). "This evidence suggests that activation of the YAP1–Nr4a1 pathway may slow brain aging and mitigate neurodegenerative diseases associated with aging." (PMID 40468463, 2025). "Therefore, careful modulation of YAP1 is essential for managing brain aging and neurodegenerative diseases." (PMID 40468463, 2025). "In this study, we propose a mechanism by which the downregulation of circSMAD4 under abnormal stress leads to decreased stability and nuclear translation of Yap1 mRNA, which may provide a new target for the treatment of degenerative diseases of the articular cartilage." (PMID 39936497, 2025).
hematologic cancers (4 papers, 2020 to 2025). "It was reported that low YAP1 level in hematological cancers resulted in an improved DNA repairing process, which facilitated cell proliferation and improved oncogenicity." (PMID 35059315, 2021). "It is noteworthy that YAP1 appears to play a tumor suppressive role in hematological cancers, which contrasts with its oncogenic function in most solid tumors." (PMID 33178690, 2020). "YAP1 gene loci are frequently deleted in hematological cancers, and YAP1 expression or inhibition of MST1 results in inhibited growth and increased apoptosis." (PMID 33178690, 2020). "The expression level of YAP1 is relatively low in hematologic cancers." (PMID 35059315, 2021). "Unlike solid tumors, knocking down MST1 or increasing YAP1 expression in hematopoietic tumors inhibits growth and leads to apoptosis." (PMID 40573272, 2025).
metabolic disorders (3 papers, 2022 to 2025). "The protein encoded by the YAP1 gene plays a key role in one of the pivotal mechanisms that govern cellular/organismal metabolism and contributes to the pathogenesis of metabolic diseases." (PMID 35884992, 2022). "Recent studies have shown that Hippo–YAP1/TAZ pathway is involved in the regulations of metabolism disorders, senescence, ferroptosis, inflammation, and fibrosis in MASLD, but their complex connections and contrast roles are also reported." (PMID 39917623, 2025). "YAP1 is an intriguing protein with an established role in cellular metabolism and the pathophysiology of metabolic diseases." (PMID 35884992, 2022). "In addition, Hippo–YAP1/TAZ pathway has been recently found to regulate metabolic disorders, which induce senescence and ferroptosis, which are hot toptics in the research of MASLD." (PMID 39917623, 2025). "Moreover, the Hippo-YAP1/TAZ pathway is involved in the regulation of senescence and ferroptosis, inflammation, and fibrosis caused by metabolic disorders in the MASLD." (PMID 39917623, 2025). "The Hippo-YAP1/TAZ pathway is also found to regulate metabolic disorders." (PMID 39917623, 2025). "In this review, we highlight the regulation and mechanism of the Hippo-YAP1/TAZ pathway in metabolism disorders, cellular senescence, ferroptosis, inflammation, and fibrosis on the progression of MASLD, which may offer new insights for developing effective treatment strategies for MASLD." (PMID 39917623, 2025).
bacterial infection (2 papers, 2020 to 2021). "After screening 10 serine/threonine phosphatases, we identified that PP2A phosphatase was involved in the activation of YAP-1/YAP after intestinal barrier loss induced by bacterial infections." (PMID 32857822, 2020). "In this study, bacterial infections reduced the phosphorylation of YAP-1/YAP in C. elegans during the disruption of intestine barrier." (PMID 32857822, 2020). "Genetic inactivation of yap-1 and egl-44 significantly reduced the survival rate and promoted bacterial accumulation in worms after bacterial infections." (PMID 32857822, 2020). "Both yap-1 and egl-44 are required for resistance to bacterial infection in worms and mice." (PMID 32857822, 2020). "Thus, EGL-44/TEAD and YAP-1/YAP play an important role in innate immune responses to bacterial infections." (PMID 32857822, 2020). "A strong temporal relationship between the permeability of intestinal barrier and the nuclear translocation of YAP-1/YAP raises the possibility that disruption of the epithelial barrier by bacterial infection could activate YAP-1/YAP." (PMID 32857822, 2020). "YAP-1/YAP was activated when the E-cadherin complex was disturbed and the intestinal barrier was disrupted during bacterial infections." (PMID 32857822, 2020).
digestive tumors (2 papers, 2022 to 2023). "In summary, our research system meta-analyzed the relationship between the expression of YAP1 and the prognosis of digestive system tumors." (PMID 35911146, 2022). "In order to further verify our findings, we used the TCGA database to analyze the expression of YAP1 in digestive system tumors." (PMID 35911146, 2022). "Then, we analyzed the correlation between YAP1 expression and prognosis of patients with digestive system tumors." (PMID 35911146, 2022). "In addition, we also performed a verification analysis through The Cancer Genome Atlas (TCGA) database to further confirm the relationship between YAP1 and the prognosis of malignant digestive tumors." (PMID 35911146, 2022). "However, the prognosis of malignant digestive tumors with YAP1 expression is still controversial." (PMID 35911146, 2022). "While correlation does not necessarily imply causation, these findings suggested that the relationship between NF1 and YAP1 in NOZ cells may also occur in primary GBC tumors and could potentially be a common feature in gastrointestinal tumors." (PMID 37147639, 2023).
inflammation (2 papers, 2023 to 2024). Aberrant reaction of the microcirculation characterized by movement of fluid and leukocytes from the blood into extravascular tissues. "Overall, these results demonstrate that YAP1 in lung macrophages is involved in the imbalance of M1/M2 polarization and pulmonary inflammation during the development of ALI." (PMID 37287755, 2023). "We hypothesized that inhibition of YAP1 activity could promote M2 macrophage polarization and alleviate pulmonary inflammation and lung injury following ALI." (PMID 37287755, 2023). "Furthermore, inhibition of YAP1 by Vt, VPs, or MVPs significantly reduces the percentage of MMP13‐positive cells in the synovial explants, corroborating previous findings that inhibition of YAP1 can regulate synovial inflammation." (PMID 38044289, 2024).
benign tumor (1 paper, 2022). "After quantitation and scoring, we observed that YAP1 expression was higher in malignant than in benign tumor samples." (PMID 35449153, 2022).
kidney diseases (1 paper, 2024). "The role of YAP1 in kidney disease remains a topic of ongoing debate, with existing discrepancies likely stemming from variations in experimental animal models and the specific renal compartments under investigation [26,28,]." (PMID 39608245, 2024). "Recent investigations have unveiled the involvement of YAP1 in kidney tissues, implicating its pivotal role in the pathogenesis of kidney diseases." (PMID 39608245, 2024). "The contrasting effects observed for YAP1 underscore its complex role and mechanism across various renal compartments, different stages of kidney disease progression, and diverse contexts of kidney disease types." (PMID 39608245, 2024).
myopathy (1 paper, 2022). A disease of the muscle in which the muscle fibers do not function properly. "In contrast, a transgenic knock-in mouse with constitutively active YAP1 in skeletal muscle exhibited muscle atrophy and myopathy." (PMID 35805114, 2022).
retinopathy (1 paper, 2023). "Upon querying a single cell RNA‐seq dataset, we showed pax2 highly expressing cell types clustered with early progenitor cells.Therefore, there remains the possibility that interplay between PAX2/6 and YAP1 influences the proliferative state seen in CRB1 retinopathy." (PMID 36656098, 2023).
YAP1 also shares sentences with these, for which no sentence is quoted: porocarcinomas (7 papers); myxoid liposarcoma (5); alveolar rhabdomyosarcoma (4); CNS tumors (4); embryonal rhabdomyosarcoma (4); acute myeloid leukemia (3); endocarditis (3); glaucoma (3); lymphoid neoplasm (3); prostatic hyperplasia (3); rheumatoid arthritis (3); uterine corpus endometrial carcinoma (3); acute kidney injury (2); acute lung injury (2); adenoid cystic carcinoma (2); age (2); ankylosing spondylitis (2); Barrett esophagus (2); basal cell carcinoma (2); blood cancers (2); brain cancer (2); cardiovascular disease (2); chronic kidney disease (2); chronic obstructive pulmonary disease (2); cystic fibrosis (2); embryonal tumor (2); endocervical adenocarcinoma (2); endothelial dysfunction (2); fallopian tube (2); in situ carcinoma (2).
A further 114 diseases each share a sentence with YAP1 in 2 papers or fewer.